LINC00534 (long independently transcribed non-coding RNA 534)
Gene: Long non-coding RNA gene on chromosome 8 (90,221,341 to 90,687,863, forward strand). Ensembl gene ENSG00000253394.
Diseases named in the same sentence as LINC00534 in open-access papers:
LINC00534 is named in the same sentence as 1 disease in open-access papers, as found by Europe PMC text mining. Sharing a sentence is not in itself a finding about the gene and the disease. The quoted sentences say what the papers report.
colorectal cancer (1 paper, 2023). A primary or metastatic malignant neoplasm that affects the colon or rectum. "LINC00534 was shown to be significantly upregulated in patients with colorectal cancer and has been identified as a potential biomarker for the disease." (PMID 37873786, 2023).